CD34 (CD34 molecule)
Diseases named in the same sentence as CD34 in open-access papers (continued):
Sharing a sentence is not in itself a finding about the gene and the disease.
dermatofibrosarcoma protuberans (40 papers, 2009 to 2026). Dermatofibrosarcoma protuberans (DFSP) is a rare infiltrating soft tissue sarcoma, generally of low grade malignancy, arising from the dermis of the skin and characteristically associated with a specific chromosomal translocation t(17;22). "Dermatofibrosarcoma Protuberans is a locally aggressive fibroblastic sarcoma of the dermis and subcutis, exhibiting CD34 positivity and COL1A1-PDGFB fusion." (PMID 41446319, 2025). "Myxoid dermatofibrosarcoma, which shows spindle cells with glassy eosinophilic cytoplasm, vesicular nuclei, and focal CD34 positivity, should also be considered." (PMID 39310581, 2024). "CD34 can be positive in various spindle cell tumors and can be helpful in differentiating dermatofibrosarcoma protuberans (DFSP), which would stain positive, from dermatofibroma, which is expected to be negative." (PMID 38559584, 2024). "Dermatofibrosarcoma protuberans and giant-cell fibroblastoma also present CD34-positive dermal spindle cells." (PMID 39188505, 2024). "Recently, the locally aggressive LFLNT has been described, a tumor entity habouring NTRK-fusions, with similar morphology as dermatofibrosarcoma protuberans and co-expression of CD34, S100 and pan-TRK." (PMID 32860002, 2021). "The giant cells in Giant cell fibroblastoma are characteristically located in the inner-side of the cranny-like vasculature and CD34-positive, which is different from GCAB." (PMID 22929620, 2012). "For example, neoplastic cells are diffusely stained with CD34 in dermatofibrosarcoma protuberans." (PMID 35321515, 2022). "Although dermatofibrosarcoma protuberans (DFSP) also strongly stains for CD34 and can sometimes have a prominent myxoid change, differential diagnosis is usually straightforward due to its plaquelike macroscopy, storiform growth pattern, and monotonous appearance." (PMID 33802620, 2021). "In the examples with neoplastic CD34+ stromal cells, we paid particular attention to the characteristics of their nuclei in dermatofibrosarcoma—barely considered in the literature—and the CD34 arrangement around vessels in sclerosing fibroma (perivascular CD34+ stromal cell collagenoma)." (PMID 34298962, 2021). "For instance, CD34 is diffuse positive in dermatofibrosarcoma protuberans." (PMID 32566457, 2020). "In the soft tissues and dermis, dermatofibrosarcoma protuberans (DFSP) may be CD34 positive but lacks the characteristic vascular pattern of SFT." (PMID 27672467, 2016). "In addition, pleomorphic lipoma should be distinguished with giant cell fibroblastoma, which is also positive for CD34 expression and possesses multinucleate giant cells." (PMID 23786924, 2013). "In addition, the differential diagnosis also includes giant cell fibroblastoma, pleomorphic fibroma and giant cell angiofibroma, which also show CD34 positive expression and possess multinucleated giant cells." (PMID 23148444, 2012). "CD34-PDFs have features that overlap with dermatofibrosarcoma protuberans (DFSP), a locally aggressive low-grade superficial sarcoma." (PMID 37337490, 2023). "Regarding CD34 positivity, this is also seen in SCL, cellular angiofibroma, low-grade malignant peripheral nerve sheath tumors, and dermatofibrosarcoma protuberans, further complicating the differential diagnosis." (PMID 39493459, 2024). "Separating these tumors from dermatofibrosarcoma protuberans (DFSP, CD34-positive tumors) requires using a large panel of immunostains." (PMID 36672995, 2023). "Immunohistochemistry (CD68-, CD10-, and Factor XIIIa-positive; CD34-negative) distinguished dermatofibroma from dermatofibrosarcoma protuberans, which shows deeper infiltration and CD34 positivity." (PMID 40981342, 2025). "Immunohistochemical staining for CD34 was negative, helping to rule out both hemangiomas and dermatofibrosarcoma protuberans." (PMID 39866529, 2025).
dermatofibrosarcoma protuberans (continued). "Immunohistochemistry is critical for distinguishing dermatofibromas (Factor XIIIa-positive and CD34-negative) from dermatofibrosarcoma protuberans (CD34-positive and Factor XIIIa-negative)." (PMID 40981342, 2025). "Dermatofibromas usually express Factor XIIIa and are negative for CD34, which helps differentiate them from dermatofibrosarcoma protuberans (CD34-positive and Factor XIIIa-negative)." (PMID 40981342, 2025). "A positive staining of CD34 and a negative staining of Factor XIIIa are observed in dermatofibrosarcoma protuberans; a negative staining of CD34 and a positive staining of Factor XIIIa are observed in dermatofibroma." (PMID 24371537, 2013). "Typically, cells of dermatofibrosarcoma protuberans are diffusely labeled with CD34 and are negative for factor XIIIa, distinguishing it from analogous neoplasms." (PMID 23199263, 2012). "Immunostaining that is positive for CD34 and negative for S100 distinguishes a dermatofibrosarcoma protuberance from diffuse neurofibroma." (PMID 19568560, 2009). "Notably, the lesion was negative for CD34, effectively ruling out dermatofibrosarcoma protuberans, which typically demonstrates strong CD34 positivity." (PMID 40981342, 2025). "Dermatofibrosarcoma protuberans are often CD34 diffuse positive and STAT6 negative." (PMID 32566457, 2020). "Dermatofibrosarcoma protuberans were CD34 diffusely positive and STAT6 negative." (PMID 32566457, 2020). "Another disease in which FXIII-A has stood the test of time and is used in the diagnosis is dermatofibroma (DF) where the spindle-shaped cells are FXIII-A positive but negative for CD34, in contrast to dermatofibrosarcoma protuberans (DFSP) where the cells are negative for FXIII-A and CD34 positive." (PMID 28894750, 2017). "Stains were negative for AE1/3, HHV-8, DOG1, CD34, S100, CD56, SMA, and Desmin, consistent with a fibrohistiocytic origin and most suggestive of dermatofibrosarcoma protuberans (DFSP)." (PMID 41200607, 2025).
HIV-1 infection (39 papers, 2005 to 2025). The type species of lentivirus and the etiologic agent of acquired immunodeficiency syndrome (AIDS). "A recent study using a humanized mouse model further described depletion of bone marrow CD34+ cells following CCR5-tropic HIV-1 infection in a CXCR4-associated manner." (PMID 30761146, 2019). "The CD34+CD7+ progenitors were further analyzed to better understand their association with HIV-1 infection." (PMID 30761146, 2019). "HIV-1 peptides containing 36 or 46 amino acids from HR2 have been shown to inhibit HIV-1 infection in primary T cells when conjugated to membrane-associated scaffold proteins derived from the nerve growth factor receptor or CD34." (PMID 27855210, 2016). "However, impaired lineage development has also been linked to the depletion of CD34+CD38− progenitors mediated by plasmacytoid dendritic cells (pDCs) in chronic HIV-1 infection." (PMID 36230931, 2022). "Other research groups have reported that the loss of CD34+ cells in CCR5-tropic HIV-1 infection might be dependent on plasmacytoid dendritic cells (pDCs) or correlated with CXCR4 expression (Tsukamoto, 2018)." (PMID 32154191, 2020). "On the other hand, the present study utilizing coculture of HIV-infected CD34+ cells and OP9-DL1 showed that CXCR4-tropic HIV-1 infection may also cause rapid depletion of CD34+CD7+CXCR4+ cells." (PMID 30761146, 2019). "HIV-1 infection causes the upregulation of inflammatory cytokine production that may affect the dynamics and functions or induce Fas-mediated apoptosis of bone marrow CD34+ cells." (PMID 30862061, 2019). "We next set out to develop an approach for studying HIV-1 infection of in vitro differentiated megakaryocytes derived from these cord blood CD34+ HSPCs." (PMID 39354676, 2025). "In this study we found that the HIV-1 infection of cord blood CD34+ cell-derived megakaryocyte precursors inhibits IFITM3 expression on Day 7 post-infection when megakaryocytes are terminally differentiated in vitro." (PMID 39354676, 2025). "We evaluated the effects of the caspase-1 inhibitor VX-765 on HIV-1 infection in humanized NSG mice engrafted with human CD34+ hematopoietic stem cells." (PMID 36800238, 2023). "Here, we further delineated the susceptibility of defined HSPC subsets (CD34+CD38+ progenitors, MPPs, and HSCs) to X4 HIV-1 infection." (PMID 36230931, 2022). "After engraftment and establishment of HIV-1 infection in hu-CD34 + NSG mice, two weeks of oral ART therapy was followed by six doses of exosomes." (PMID 34545097, 2021). "Here we have demonstrated that the effect of HIV-1 infection on erythroid development suggested by the results with the SCID/hu mouse experiments that can be reproduced by expression of nef in CD34 + cells." (PMID 34930406, 2021). "CD34 mice have most often been used in a therapeutic setting to test the anti-viral potency of new drugs following the establishment of systemic HIV-1 infection." (PMID 33673566, 2021). "Upon HIV-1 infection, cell distributions of immune cells but also of CD34+ stem cells are profoundly modified in PB and BM." (PMID 33102251, 2020). "A reduction of bone marrow CD34+ cell counts after CCR5-tropic HIV-1 infection was also detected in another study." (PMID 30862061, 2019). "It is desirable to transduce activated CD4+ T cells, the natural targets of HIV-1 infection, and CD34+ HSPCs, which can differentiate to form new CD4+ T cells." (PMID 31778955, 2019). "Mice transplanted with human CD34+ HSPCs to study HIV-1 infection are valuable tools to address questions about HIV-1 pathobiology and treatment." (PMID 29361613, 2018). "In the current study, our infected humanized mice showed higher frequencies of CD34+ cells during HIV-1 infection compared to uninfected control animals." (PMID 28279181, 2017).
HIV-1 infection (continued). "Strikingly, depletion of plasmacytoid dendritic cells (pDCs) prevented human CD34+CD38- early HPCs from HIV-1 infection-induced depletion and functional impairment and restored the gene expression profile of purified CD34+ HPCs in humanized mice." (PMID 28759657, 2017). "The distribution of human immunocytes in the brain varied, and was comparable to that previously observed in humanized mice created by CD34+ cell transplantation and subsequent HIV-1 infection." (PMID 29084769, 2017). "Further analysis indicated that the frequency of CD34+CD38- early HPCs was largely decreased in humanized mice with chronic HIV-1 infection, while the proportion of intermediate CD34+CD38+ HSCs was relatively expanded." (PMID 28759657, 2017). "The results indicate that proliferation of human CD34+ cells in the BM was inhibited by approximately 3-fold in chronic HIV-1 infection compared to the mock animals." (PMID 28759657, 2017). "The depletion of CD34+CD38- early HPCs in human BM from HIV-1 infection was strengthened by the addition of more patients (n = 5)." (PMID 28759657, 2017). "In this study, we found that CD34+CD38- early HPCs were preferentially depleted during chronic HIV-1 infection, which correlated with the depression of hematopoiesis development and dysregulated gene expression in bulk Lin-CD34+ HPCs." (PMID 28759657, 2017). "CD34+ haematopoetic cells (HPCs) also serve as a viral reservoir, since a subpopulation of CD34+ HPCs expresses CD4 and CCR5 and/or CXCR4 and these cells are susceptible to HIV-1 infection." (PMID 22548060, 2012). "Much higher frequencies of HIV-1 infection of CD34+ cells were reported within Zairian patients with HIV disease (36.5%)." (PMID 19112504, 2008). "With an aim of generating DCs from a renewable source for HIV-1 studies, here we evaluated the capacity of hES cell derived CD34+ cells to give rise to DCs which can support HIV-1 infection." (PMID 18215326, 2008). "Similar to that of fetal liver CD34 cell derived cells, the hES-CD34 macrophages also supported HIV-1 infection although the levels of viral yield differed somewhat." (PMID 16623949, 2006). "To extend these results to a stem cell gene therapy setting, here we show transduction of primary CD34+ hematopoietic progenitor cells to derive normal end stage cells that are resistant to HIV-1 infection." (PMID 16109172, 2005). "Human CD34+ HSC reconstituted models facilitate studies of progressive chronic HIV-1 infection." (PMID 40309515, 2025). "Furthermore, we demonstrated that the virus-induced hematopoietic inhibition occurred despite the CD34+ cells being resistant to HIV-1 infection." (PMID 38721526, 2024). "Earlier reports of the association of miRNAs expressed by either CD34+ HSPC or CD4+ T-helper cells were not known to be dependent on any role or influence of HIV-1 infection in the context of dys/regulation of hematopoiesis." (PMID 38721526, 2024). "The absence of CCR5 receptor and the increased expression of antiviral restriction factors may play a key role in protecting the CD34+CD90+ HSCs population from HIV-1 infection during pre and post manipulation." (PMID 35359982, 2022). "Another recent study suggested that CD34+CD7+CXCR4+ cells may be depleted in response to CXCR4-tropic HIV-1 infection in a coculture of HIV-infected umbilical cord-derived CD34+ and OP9-DL1 cells (Tsukamoto, 2019b)." (PMID 32154191, 2020). "On the other hand, among various steps in T-lineage development, the functional and numerical alteration of CD34+ LPs in HIV-1 infection needs to be further elucidated to improve the current understanding of the degree of impaired CD4+ T-cell generation on peripheral CD4+ T-cell loss and AIDS onset." (PMID 32154191, 2020). "Further studies may be designed to test shorter coculture periods than 1 week and/or investigate the association of HIV-1 infection with factors that regulate the expression of CD3, CD4, CD7, and CD34." (PMID 30761146, 2019).
HIV-1 infection (continued). "Consistent with the preferential reduction of CD34+CD38- HPCs, BrdU-positive CD34+CD38- early HPCs were significantly decreased by chronic HIV-1 infection; meanwhile, the proliferation of CD34+CD38+ intermediate HPCs was only mildly reduced by chronic HIV-1 infection." (PMID 28759657, 2017). "Here, humanized NOD-Rag1−/− γc−/− mice differentially reconstituted with human CD34+ -enriched hematopoietic stem cells (Hu-mice), were used to assess target cell frequency and viral inoculation dose as determinants of HIV-1 infection following intravaginal (IVAG) challenge." (PMID 29127409, 2017). "The hematopoietic cell lineage was the most affected pathway induced by chronic HIV-1 infection among the top 15 pathways, whereas those dysregulated genes were also significantly restored to mock levels in pDC-depleted BM CD34+ HPCs of humanized mice chronically infected with HIV-1." (PMID 28759657, 2017). "Notably, the depletion of pDCs significantly changed the percentage of CD34+CD38- early HPCs in the BM from humanized mice with chronic HIV-1 infection." (PMID 28759657, 2017). "In addition, the cell counts of CD34+CD38+ intermediate HPCs showed only minor recovery by the depletion of pDCs during chronic HIV-1 infection, which is consistent with the slight decrease in proportion of CD34+CD38+ intermediate HPCs." (PMID 28759657, 2017). "Chronic HIV-1 infection of NOD/scid-IL-2Rgcnull mice transplanted with human CD34+ hematopoietic stem cells (CD34-NSG) leads to persistent viremia, profound CD4+ T lymphocyte loss and infection of human monocyte-macrophages in the meninges and perivascular spaces." (PMID 25523827, 2014). "Interestingly, a higher restriction in HIV-1 infection was achieved by engrafting mice with transduced CD4+ T cells than with transduced CD34+ HSC cells." (PMID 24167505, 2013). "A pioneer study by Anderson and Akkina showed that human macrophages differentiated in vitro from CD34+ HSCs and transduced with rhesus macaque TRIM5α resisted HIV-1 infection, thus providing the proof of principle that TRIM5α could be used in gene therapy." (PMID 24167505, 2013). "Later studies that demonstrated HIV-1 infection of HPCs were also performed with mixed CD34+ populations prepared from the BM, which included early progenitors along with some more differentiated and lineage-committed CD34+ cells." (PMID 19112504, 2008). "Both non transduced and lentiviral vector transduced hES cells were found to be capable of generating CD34 cells that give rise to macrophages which could support productive HIV-1 infection." (PMID 16623949, 2006). "Additionally, we showed that LentiCRISPR/SaCas9-mediated disruption of CCR5 was effective in CD34+ HSPCs, and whether engraftment of CCR5-edited CD34+ HSPCs into humanized mouse resistance to HIV-1 infection requires further exploration." (PMID 31186067, 2019). "We reported that the two human T-cell-specific miRNAs, miR-15a and miR-24, were differentially regulated in HIV-1 infection and impaired myelopoiesis (CFU-GM) and erythropoiesis (BFU-E) of the CD34+ cells." (PMID 38721526, 2024). "In this study, we show that CD34+CD90+HSC fraction of HSPCs have reduced CD4/CCR5 receptors and increased antiviral restriction factors to limit the HIV-1 infection and demonstrate that they are the potential target cells for CCR5 gene editing." (PMID 35359982, 2022). "In order to assess the quality of in vivo human HPCs during chronic HIV-1 infection, we measured CFU activity of purified human Lin-CD34+ HPCs from mock- or HIV-1-infected humanized mice, including GM, E and GEMM." (PMID 28759657, 2017). "The present study demonstrates, for the first time, that human CD34+CD38- early HSCs are subject to preferential depletion and functional impairment in vivo in the BM of humanized mice with chronic HIV-1 infection, in a pDC-dependent fashion." (PMID 28759657, 2017).